BAG1 (BAG cochaperone 1)
Diseases named in the same sentence as BAG1 in open-access papers (continued):
Sharing a sentence is not in itself a finding about the gene and the disease.
ductal carcinoma in situ (2 papers, 2016 to 2017). "Overexpression of Bag-1 mRNA in MCF-10A is known to produce acini with luminal filling reminiscent of ductal carcinoma in situ." (PMID 27043661, 2016). "Positive BAG-1 staining is also found in the ductal carcinoma in situ component of some ER+ tumours, suggesting that upregulation of BAG-1 can occur relatively early in tumourigenesis and may be dependent on hormonal status." (PMID 28510570, 2017). "We then examined the effect of a small-molecule inhibitor of Bag-1, Thio-2, in Bag-1L-driven premalignant change in this experimental model of ductal carcinoma in situ to determine whether these changes might be amenable to therapeutic intervention." (PMID 27043661, 2016).
head and neck squamous cell carcinoma (2 papers, 2017 to 2021). A squamous cell carcinoma that arises from any of the following anatomic sites: lip and oral cavity, nasal cavity, paranasal sinuses, pharynx, larynx, and salivary glands. "Over-expression of BAG1 in head and neck squamous cell carcinomas (HNSCC) is associated with cisplatin-resistance." (PMID 33581726, 2021).
Huntington disease (2 papers, 2011 to 2022). Huntington disease (HD) is a rare neurodegenerative disorder of the central nervous system characterized by unwanted choreatic movements, behavioral and psychiatric disturbances and dementia. "This gene participates in the pathway map named HSP70 and HSP40-dependent folding in Huntington’s disease BAG-1." (PMID 35804531, 2022).
ischemia (2 papers, 2015 to 2021). A hypoperfusion of the BLOOD through an organ or tissue caused by a PATHOLOGIC CONSTRICTION or obstruction of its BLOOD VESSELS, or an absence of BLOOD CIRCULATION. "The results of the present study demonstrated that Bag-1L can protect alveolar cells from apoptosis induced by simulated ischemia/reperfusion, and this is consistent with previous research showing that Bag-1 can suppress apoptosis in diverse systems." (PMID 34056003, 2021). "Before the onset of simulated ischemia, mRNA expression of the anti-apoptotic factors BCL-XL and BAG1 was similar in preconditioned and non-preconditioned CB-MSCs, whereas BCL-2 expression was suppressed by HP (relative expression: 1.6±0.1×10−4 vs. non-HP 3.6±0.3×10−4; P < 0.01)." (PMID 26380983, 2015).
metastatic cancer (2 papers, 2022). A carcinoma which has spread from the original site of growth to another anatomic site. "The Bag-1 expression is significantly upregulated in primary and metastatic cancer patients compared to normal breast tissue." (PMID 34995286, 2022).
neuroblastoma (2 papers, 2013 to 2021). Neuroblastoma (NB) is the most common solid, extracranial childhood tumor. "Our results could explain the link between the expression of ERα and the down-regulation of main players modulating apoptosis (caspase-3, BAG3, BAG1) recently described in human neuroblastoma in absence of ligand." (PMID 23825704, 2013).
oral squamous cell carcinoma (2 papers, 2002 to 2011). "Bag-1 expression is deregulated in oral squamous cell carcinoma (SCC), with increased expression associated with progression, metastasis and poor prognosis in early stage tumours and increased cytoplasmic Bag-1 in lymph node metastases." (PMID 21522149, 2011).
osteosarcoma (2 papers, 2018 to 2019). A usually aggressive malignant bone-forming mesenchymal neoplasm, predominantly affecting adolescents and young adults. "In human osteosarcoma U2OS MYC-ER cells where BAG1 induction was blocked, activation of MYC resulted in substantial apoptotic cell death." (PMID 30902071, 2019).
pancreatic carcinomas (2 papers, 2006 to 2019). "Therefore, enhanced expression of MKP-1, SGK-1, X-IAP and Bcl-2 but not of BAG-1 may be involved in DEX-induced therapy resistance of pancreatic carcinomas." (PMID 16539710, 2006).
parasite infection (2 papers, 2009 to 2022). "Host cell clustering combined with parasite infection and differentiation status assignment revealed that a substantial proportion of BAG1+ cells were clustered into #A–#F clusters." (PMID 35372115, 2022). "Differentiation was monitored using genetic markers (BAG1, SAG1, SAG4) and by scoring changes in parasitemia and number of parasites per vacuole (data not shown)." (PMID 19277211, 2009).
prostate tumor (2 papers, 2012 to 2023). "The Bag-1 peptide that we found to inhibit prostate tumor cell growth has a length of 68 amino acids, comprising helix 1 of the BAG domain at its C-terminus and another twenty amino acids at its N-terminus from the ubiquitin-like domain." (PMID 23049684, 2012).
Stroke (2 papers, 2023 to 2025). Sudden impairment of blood flow to a part of the brain due to occlusion or rupture of an artery to the brain. "In terms of BAG1’s neuroprotective effects, overexpression of BAG1 reduces injury after a stroke and promotes axonal outgrowth after an optic nerve crush." (PMID 40777354, 2025).
acute leukemia (1 paper, 2011). A clonal (malignant) hematopoietic disorder with an acute onset, affecting the bone marrow and the peripheral blood. "We analyzed the expression of three major BAG1 protein isoforms, BAG1L, -1M, and BAG1, in bone marrow samples from 10 childhood patients with acute leukemia at the moment of diagnosis and compared it with BAG1 expression in 5 healthy bone marrow (HBM) specimens." (PMID 22016818, 2011).
acute lymphoblastic leukaemia (1 paper, 2021). "The investigation of BAG1 isoforms expression and intracellular localization in B‐cell acute lymphoblastic leukaemia (B‐ALL) patient‐derived specimens revealed that BAG1 levels decrease during disease remission, compared to diagnosis, but drastically increase at relapse." (PMID 34402163, 2021).
B-cell chronic lymphocytic leukemia (1 paper, 2013). "Thus it has been shown that both UCN-01 and flavopiridol decrease the expression of Mcl-1, XIAP, BAG-1, and Bcl-2 in B-cell chronic lymphocytic leukemia cells." (PMID 23527225, 2013).
behavioral disorders (1 paper, 2021). "BAG1 overexpression under an NSE-promoter promoted recovery from stress-induced behavioral disorders." (PMID 34698102, 2021). "In the literature, BAG1 assisted recovery from stressful adverse effects and from behavioral disorders such as mania and depression in mice." (PMID 34698102, 2021).
bladder cancer (1 paper, 2021). "The potential role of BAG1 and PRKCD in bladder cancer has not been reported." (PMID 33925460, 2021).
cholangiocarcinoma (1 paper, 2023). A carcinoma that arises from the intrahepatic biliary tree (intrahepatic cholangiocarcinoma) or from the junction, or adjacent to the junction, of the right and left hepatic ducts (hilar cholangiocarcinoma). "In cholangiocarcinoma, miR-138 targets Bag-1 and inhibits cell proliferation." (PMID 38002064, 2023).
cognitive decline (1 paper, 2021). "Estrogen deficiency by VCD decreases ChAT, BDNF, and BAG1 and consequently leads to cognitive decline and depression-related behaviors." (PMID 34698102, 2021).
colorectal tumors (1 paper, 2019). "The anti-apoptotic BAG-1 protein isoforms are known to be overexpressed in colorectal tumors and are considered to be potential therapeutic targets." (PMID 31504805, 2019).
dysplasia (1 paper, 2011). A usually neoplastic transformation of the cell, associated with altered architectural tissue patterns. "All of the cell lines expressed high levels of Bag-1 compared with normal epidermal keratinocytes, and three SCC cell lines (MET4, SCC-13 and BICR19) showed higher levels of all three Bag-1 protein isoforms than the PM1 and PM3 dysplasia cell lines." (PMID 21522149, 2011). "As Bag-1 expression was elevated in a subset of tumours, the hypothesis was that at least some of the SCC cell lines would express higher levels of Bag-1 than the normal epidermal keratinocytes and dysplasia cell lines." (PMID 21522149, 2011).
endometrial carcinoma (1 paper, 2007). A malignant tumor arising from the epithelium that lines the cavity of the uterine body. "Both BAG1 and bcl-2 play a role in the inhibition of apoptosis in endometrial carcinoma." (PMID 17645802, 2007).
esophageal cancer (1 paper, 2021). A primary or metastatic malignant neoplasm involving the esophagus. "Overexpression of BAG-1 has closely related to cell differentiation and TNM stage in esophageal cancer and its downregulation inhibits the proliferation and invasion of human esophageal carcinoma cells." (PMID 33581726, 2021).
intervertebral disc degeneration (1 paper, 2023). "However, additional studies are needed to confirm the effects of Bag-1 and its potential interaction with other intracellular signaling factors that may play an important role in understanding the pathogenesis of intervertebral disc degeneration and its treatment." (PMID 36979842, 2023).
invasive ductal carcinoma (1 paper, 2009). "In summary, we have demonstrated that the high BAG-1 expression is associated with the luminal A phenotype, is an independent predictor of outcome and may indicate enhanced responsiveness to tamoxifen in ER+ invasive ductal carcinoma." (PMID 19066611, 2009). "BAG-1 protein expression was assessed using immunohistochemistry in 292 patients with invasive ductal carcinoma and correlated with clinicopathological variables, therapeutic response and disease outcome." (PMID 19066611, 2009).
kidney cancer (1 paper, 2020). Primary or metastatic malignant neoplasm involving the kidney. "This also brought us new thinking about the roles of BAG1 and ATG16L2 in kidney cancer." (PMID 32780567, 2020).
lung adenoma (1 paper, 2004). A benign, well circumscribed epithelial neoplasm that arises from the bronchus or the lung parenchyma. "We show that BAG-1 heterozygosity in mice impairs C-Raf oncogene-induced lung adenoma growth." (PMID 15560850, 2004).
metastasis (1 paper, 2021). The spread or migration of cancer cells from one part of the body (where they first appeared) to another. "However, inconsistent with other studies, our observations showed that low BAG1 expression in KIRC correlated significantly with aggressive tumor progression toward more malignant phenotypes including clinical stage, grade, tumor size, lymph node metastasis and distant metastasis." (PMID 33581726, 2021).
metastatic melanoma (1 paper, 2018). A melanoma that has spread from its primary site to another anatomic site. "An additional way to evaluate the potential prognostic values of BAG1, PEX3, and WIPI1 was carried out by assessing their expression in primary vs metastatic melanoma samples." (PMID 30622661, 2018).
mood disorder (1 paper, 2021). A cognitive disorder a disturbance in which the person's mood is hypothesized to be the main underlying feature. "Bag-1, an identified target for the actions of mood stabilizers, seems to have an important role in the development of mood disorders while therapies designed to enhance the function of Bag-1 may modulate the effects of stress hormone." (PMID 34205227, 2021).
peritoneal cancer (1 paper, 2016). A peritoneum cancer that is located in the inside of the abdomen. "Deregulation of the expression of BAG1, CCNB1, MKI67, and MYBL2 was documented in PC biopsies, suggesting that growth and cell proliferation pathways are disturbed, a feature of malignant transformation in ovarian and peritoneal cancer that has been widely documented in the literature." (PMID 27542596, 2016).
proteinopathy (1 paper, 2019). "Conversely, inhibition of dynein-dependent retrograde transport of aggregated proteins to perinucleus aggresomes diverted neurons to activate proteasomal autophagy and reduced protein aggregates in a BAG1 dependent manner with implications in proteinopathy in motoneuron diseases." (PMID 31209204, 2019).
renal carcinoma (1 paper, 2018). A carcinoma arising from the epithelium of the renal parenchyma or the renal pelvis. "BAG1 also shows a favorable prognostic value in renal cancer (p < 0.0001)." (PMID 30622661, 2018).
respiratory failure (1 paper, 2025). The significant impairment of gas exchange within the lungs resulting in hypoxia, hypercarbia, or both, to the extent that organ tissue perfusion is severely compromised. "Regarding the associations between HSPs SNPs and respiratory failure indicators, we found that rs6457452 HSPA1B (p = 0.03) and rs753856 HSPA6 (p = 0.02) were linked to prolonged oxygen therapy, whereas rs706121 BAG1 (p = 0.04) decreased the duration of lug ventilation, indicating a better prognosis." (PMID 41009536, 2025).
squamous cell carcinoma of the (1 paper, 2002). "Several groups have studied expression of BAG-1 in human squamous cell carcinomas." (PMID 12373595, 2002).
tauopathy (1 paper, 2025). Neurodegenerative disorders involving deposition of abnormal tau protein isoforms (tau proteins) in neurons and glial cells in the brain. "This analysis led us to focus on interactions between EVA1C, HSP70, and BAG1, which were subsequently validated in selected experimental models of tauopathy." (PMID 41202143, 2025). "Consistent with the cell-based results, IF data showed that NR reduced the colocalization between EVA1C/BAG1 in tauopathy mice but not EVA1C/HSP70." (PMID 41202143, 2025).
type 2 diabetes (1 paper, 2026). "Many additional gene products linked to ER quality control–dependent ubiquitin-proteasomal proteolysis also show genetic evidence of linkage to human type 2 diabetes (such as EDEM3, UFD1, NPL4, BAG1, and FAF1)." (PMID 41252202, 2026).
cancer (58 papers, 2002 to 2025). A tumor composed of atypical neoplastic, often pleomorphic cells that invade other tissues. "They identified BCL2-associated athanogene-1 (BAG1) as a potential target due to its increased expression during cancer relapse." (PMID 38611039, 2024). "Although several studies determined the direct or indirect network between PIK3CA, KDR, GAB1, VEGFA, PLCG, and CRKL and hsa-miR-429 in various cancers, the functional regulation of these genes in Bag-1 deficiency conditions is still needed to elucidate." (PMID 37533517, 2022). "BCL2 associated Athano-Gene 1 (BAG1) has been described to be involved in the development and progression of cancer." (PMID 33581726, 2021). "BAG1 is often overexpressed in human cancer and elevated BAG1 levels is associated with poor prognosis." (PMID 30902071, 2019). "Bag-1 (Bcl-2-associated athanogene) is a multifunctional anti-apoptotic protein frequently overexpressed in cancer." (PMID 31883527, 2019). "In this study, we have clearly identified the role of FLJ20420 as a BAG-1 transcription factor, and also linked its expression to sensitivity to cisplatin-induced apoptosis in cancer cells." (PMID 22567091, 2012). "To understand the molecular regulation of BAG-1 expression in human cancer, we have identified a cDNA that encodes a novel BAG-1 transcription factor, termed FLJ20420, using a protein-DNA fragment interaction cloning technique." (PMID 22567091, 2012). "Bcl-2-associated athanogene-1 (Bag-1) expression is deregulated in a variety of human tumours, including cancers of the breast, lung, colon, oesophagus, larynx, oral cavity and tongue." (PMID 21522149, 2011). "The inhibitory function of BAG-1 was more pronounced for p73α, compared with p73β, a splice variant that is transcriptionally active and is frequently co-expressed in cancer cells." (PMID 19293798, 2009). "High-level expression of Bcl-2 associated athanogene (BAG-1) protects cancer cells from stress-induced cell death and growth inhibition." (PMID 19293798, 2009). "The six thermogenes include HSP90AA1 and HSPA4, common in thermoresistance and DAMPs/ICD, DNAJB5, the protein product of which has the highest estimated thermostability, and HSPA1A, HSP90AB1, and BAG1, which are implicated in cancer-relevant pathways (underlined)." (PMID 31814876, 2019). "Bcl-2 and Bag-1 are associated with chemotherapy resistance in cancer cells." (PMID 18430249, 2008). "Importantly, overexpression of BAG-1 is linked to various human cancers, and may serve as an independent prognostic factor in the management of certain cancers." (PMID 22179630, 2012). "It will be important to consider these results and the implications for targeting BAG-1 isoforms in prostate and other cancers." (PMID 38412481, 2024). "The reciprocal negative interactions of melatonin and the GR, including via BAG-1, also modulate hypothalamic fluxes with consequences for cancer pathoetiology and dynamic intercellular interactions in the tumor microenvironment." (PMID 37970210, 2023). "The interactions of pineal melatonin/BAG-1/Hsp90 with the CAR are proposed to underpin how aging and circadian dysregulation are associated with cancer risk." (PMID 37970210, 2023). "The multifunctional Bag-1 protein regulates several cellular pathways, including apoptosis, autophagy, proliferation, invasion, and metastasis in cancer cells." (PMID 37533517, 2022). "In contrast, Bag-1 knockdown and knockout cells display reduced cell viability, decreased proliferation and increased sensitivity to anti-cancer drugs." (PMID 34428256, 2021). "The ΔCt values of 11 cancer-related genes (HER2, ER, PR, BCL2, CEGP1, Ki67, STK15, STMY3, CD68, GSTM1, and BAG1) were positively associated with HDL." (PMID 34456877, 2021). "High expression levels of Bag-1 promote cell proliferation of cancer cells, and prevent drug-induced apoptosis." (PMID 34428256, 2021).